GCG (glucagon)
Diseases named in the same sentence as GCG in open-access papers (continued):
Sharing a sentence is not in itself a finding about the gene and the disease.
Hyperglycemia (continued). "In βV59M-RFP mice exposed to chronic hyperglycaemia for 4 weeks, 7% of RFP+ cells (that is, cells of β-cell lineage) contained both insulin and glucagon, and 8% expressed glucagon alone." (PMID 25145789, 2014). "For example, inappropriate glucagon secretion contributes to hyperglycemia, whereas impaired somatostatin signaling fails to adequately suppress glucagon and insulin secretion." (PMID 40919135, 2025). "Nonetheless, while GIP does not stimulate glucagon secretion in healthy individuals under conditions of hyperglycemia, it stimulates glucagon secretion in hyperglycemic subjects with T2D, and in people with hepatic cirrhosis and hyperglucagonemia." (PMID 40024571, 2025). "Furthermore, chronic hyperglycemia has been shown to upregulate hepatic GCGR expression while simultaneously impairing downstream signaling, indicating the development of hepatic glucagon resistance." (PMID 41149695, 2025). "On the other hand, maternal hyperglycemia did not promote a significant change in the glucagon-positive labeling area." (PMID 40563978, 2025). "Nevertheless, several plausible mechanisms have been proposed: Stress-induced hyperglycemia (SIH) exacerbates insulin resistance (IR) while triggering excessive release of counter-regulatory hormones, including catecholamines, cortisol, glucagon, and growth hormone." (PMID 40303637, 2025). "The specific role of carbamoyl phosphate synthetase 1 (CPS1), a rate-limiting enzyme in the urea cycle, in the development versus the persistence of glucagon-induced hyperglycemia has not been previously established." (PMID 39193349, 2024). "In youth with obesity and IGT or T2D fasting glucose and glucagon were negatively correlated and hyperglucagonemia does not appear to drive hyperglycemia." (PMID 39027470, 2024). "ZT-01 administration at the OGTT onset increased the glucagon response without exacerbating hyperglycemia (2877 ± 806 vs. 2982 ± 781), potentially due to the corresponding increase in c-peptide levels (6251 ± 5463 vs. 14008 ± 5495, p = 0.013)." (PMID 38510652, 2024). "The absence of postprandial glucagon suppression in people with T2D is established and is considered one of the pathogenetic mechanisms of hyperglycemia development." (PMID 39598143, 2024). "In RIPGLUT1; GLUT-2−/−mice, the stimulation of glucagon secretion by hypoglycemia or its suppression by hyperglycemia was lost, although GLUT-2 was not expressed in pancreatic α cells." (PMID 38333863, 2024). "While the GLP-1 reduces blood glucose by several mechanisms, including stimulating insulin secretion and suppressing glucagon release during hyperglycemia, GIP stimulates insulin release during hyperglycemia, but it also stimulates glucagon release during hypoglycemia." (PMID 36289697, 2022). "A combination of counter regulatory hormones (e.g., glucagon and growth hormone) and proinflammatory cytokines such as tumor necrosis factor alpha (TNF-α), interleukin-1 (IL-1), and interleukin-6 (IL6) lead to insulin resistance and hyperglycemia." (PMID 35178208, 2022). "As such, rebound hyperglycaemia has been observed on treatment termination with some small molecule GCGR antagonists, likely because of their actions to elevate circulating glucagon." (PMID 36005280, 2022). "The authors interpreted those results as evidence that the hyperglycemia of T1D is not dependent on the rise in plasma glucagon." (PMID 35569125, 2022). "In contrast to the effects on levels of insulin, T2DM patients with hyperglycemia often show persistent fasting hyperglucagonemia and lack of suppression of glucagon levels in the postprandial state." (PMID 36307866, 2022). "As the basal circulating glucagon levels decreased in the OMPlox/lox;GCGcre/w mice, the mRNA levels of enzymes involved in gluconeogenesis, including G-6pase (p < 0.01) and Pepck, were decreased in STZ-induced hyperglycemia." (PMID 36104518, 2022).
Hyperglycemia (continued). "Fasted and 2 h refed plasma glucagon levels suggested α-cell dysfunction, and subsequently, inappropriate glucagon release was not responsible for hyperglycemia in HFD mice." (PMID 33817571, 2021). "The present study did not isolate insulin deficiency from hyperglycemia and other metabolic changes, including an increase in BOHB, nonesterified fatty acids, and amino acids, as well as glucagon levels." (PMID 33561011, 2021). "Following oral administration of Bay 27-9955 at two doses, a significant blunting of acute hyperglycaemia was observed following a glucagon infusion, in the absence of clinical side effects." (PMID 34566894, 2021). "Lack of suppression of postprandial glucagon secretion in subjects with T2DM plays an important role in the pathogenesis of postprandial hyperglycemia." (PMID 33758717, 2021). "Similarly, hyperglycemia induces alpha cell hydrogen peroxide production, PI3K-Akt signaling, cell proliferation, and glucagon secretion." (PMID 32774668, 2020). "A significant hyperglycemia was found in the maltodextrin-treated group during the prelunch period, without any significant changes in insulin and glucagon between the two groups." (PMID 32971830, 2020). "In some patients with T2D, the normal relationship between plasma glucose and glucagon is reversed and hyperglycaemia stimulates rather than inhibits glucagon secretion." (PMID 32446876, 2020). "This was followed by sustained hyperglycemia, independent of changes in insulin and glucagon levels, in glucose disposal, or in the ability of insulin to suppress lipolysis." (PMID 29528284, 2018). "These animals lost almost all of their α cells, but the phenotype was unremarkable; however, hyperglycemia after STZ administration was not prevented by the glucagon cell ablation." (PMID 28323959, 2017). "Despite postprandial glucagon being reduced in our participants with T2D, postprandial hyperglycemia was not improved." (PMID 28744255, 2017). "However, it is becoming increasingly apparent that impaired glucagon secretion also contributes to the excessive hepatic glucose production in T2DM, exacerbating episodes of hyperglycaemia." (PMID 27044683, 2016). "The role of glucagon in the context of potential GPR39 driven hyperglycemia was not explored in this work since GPR39 is absent in alpha-cells." (PMID 26720709, 2015). "Thus, these experiments indicate that in vivo plasma glucagon levels are decreased in HFD mice under basal conditions and are impaired in response to hyperglycaemia." (PMID 26108563, 2015). "In the current study, the unchanged plasma glucagon in OZ after hemorrhage suggests that glucagon is not playing a major role in the acute hyperglycemia." (PMID 25472607, 2014). "The main finding of this study is that xylazine administration produced an acute hyperglycemia without significant changes in blood insulin, glucagon, and GLP-1 in both insulin-dependent diabetic and normoglycemic monkeys." (PMID 24138083, 2013). "Remarkably, in a cellular model of “insulin resistance,” where high concentrations of glucose and insulin are exposed to α-cells to mimic hyperglycemia and hyperinsulinemia, subsequent applications of insulin fail to increase GABAAR on the cell surface and fail to inhibit glucagon secretion." (PMID 23316165, 2012). "We recently showed that without dysregulated glucagon secretion, the combination of defective insulin secretion and peripheral insulin resistance was not sufficient to induce hyperglycemia in synaptotagmin-7 KO mice." (PMID 22046328, 2011). "Consistent with the notion, our recent study showed that in the absence of dysregulated glucagon secretion, the combination of defective insulin secretion and peripheral insulin resistance was not sufficient to induce hyperglycemia in synaptotagmin-7 KO mice." (PMID 22046328, 2011).
Hyperglycemia (continued). "EX also checks pancreatic release of glucagon in response to food (without altering the normal insulin/glucagon ratio), which prevents the liver from overproduction of sugar when it is not needed; hyperglycemia does not develop." (PMID 20582183, 2010). "Our patient had a transient hyperglycemia with the glucagon bolus, but she did not demonstrate nausea, vomiting, or hypokalemia." (PMID 18505576, 2008). "Thus, in addition to the higher inhibitory effect exerted on insulin secretion compared with glucagon, SST5 agonists may indirectly regulate plasma glucose levels by affecting GLP-1 release, and SST5-targeting drugs may result in hyperglycaemia." (PMID 39859181, 2025). "The differential glucagon response in single vs group housed mice without altered insulin, indicates that engagement of pancreatic α-cells could drive fasting hyperglycemia during chronic isolation." (PMID 41509225, 2025). "Importantly, neither study reported an increase in overall hyperglycaemia or mean glucose levels, suggesting that the addition of glucagon provides a meaningful safety benefit without compromising glycaemic control." (PMID 40718205, 2025). "Similarly, the unimolecular triple agonist SAR441255 (GLP‐1/GCG/GIP) outperforms dual agonists in preclinical studies, promoting weight loss and glucose regulation without exacerbating hyperglycemia." (PMID 40919135, 2025). "We next turned our attention to α cell–to–β cell communication and whether lack of glucagon production influences glucose homeostasis during hyperglycemia." (PMID 40971442, 2025). "In brief summary and with minor variations, augmented responses of glucagon (AUC only in hypoglycemic clamp), cortisol, and ACTH and attenuated responses of GH in both clamps correlated with unfavorable metabolic phenotypes, such as adiposity, chronic hyperglycemia, and insulin resistance." (PMID 37708362, 2024). "Many authors propose a GIP-stimulated glucagon secretion even during hyperglycemia, but this hypothesis is controversial since in Type 1 diabetes patients without insulin secretion, GIP infusion cannot stimulate glucagon secretion during hyperglycemia." (PMID 37635984, 2023). "Likewise, optogenetic stimulation of VMHNOS1 neurons causes robust hyperglycemia via activation of CRR (i.e., glucagon and corticosterone), without a suppression on insulin release." (PMID 35619170, 2022). "Since relative glucagon secretion (RGS) does not drop 40% below maximal, even during hyperglycemia, the triggering signal for glucagon granule exocytosis persists and ensures constant co-release of glutamate in the interstitial space, mirroring the plasma glutamine concentration." (PMID 35448534, 2022). "Thus, neither the relative contribution of glucagon‐induced hepatic glucose output, nor those of GR‐1 and GR‐1 receptor activation, to the hyperglycemia of T1D is clearly defined." (PMID 35569125, 2022). "However, this responsiveness to hyperglycemia is incomplete as no amount of residual C-peptide can fully suppress glucagon once a diagnosis of T1D is made." (PMID 35592786, 2022). "Additionally, when the hyperglycemia mice were subcutaneously injected with an over‐dosage of insulin (3 mg kg−1), the GRS glucagon MN patch could prevent PGLs from dropping below 50 mg dL−1 while gaining a more rapid PGL recovery 3 h post insulin challenge." (PMID 35957510, 2022). "However, if the energy-expenditure rise outlives the acute glucose raising effects (for example, due to effects on amino acid metabolism), then the absence of chronic hyperglycaemia with glucagon treatment is reassuring." (PMID 36123404, 2022). "Even in patients with early-stage T2DM where glucagon levels may not be elevated, glucagon levels are nonetheless inappropriate in the setting of hyperglycemia." (PMID 36402444, 2022). "Thus, it seems that glucagon is essential for hyperglycemia and in the absence of glucagon action, the liver fails to produce excess glucose." (PMID 35211170, 2022).
Hyperglycemia (continued). "At present, we can only speculate that while hyperglycaemia is not a potent enough suppressor of glucagon secretion, the degree of insulin secretion was sufficient to inhibit excess glucagon secretion." (PMID 34951657, 2022). "Moreover, while chronic GCG stimulation exhibits glucose intolerance, acute GCG agonism at a lower dose, which is not able to evoke hyperglycaemia, enhances glucose tolerance and improves insulin sensitivity." (PMID 34072172, 2021). "Nutrients in thedistal small bowel are a signal that the meal was significant, and GLP-1production helps to create satiety, to block gastric emptying and, even at acertain point, to block glucagon secretion to avoid hyperglycemia after muchglucose has been produced (even if none was consumed)." (PMID 32667533, 2020). "Moreover, phlorizin corrected the dysregulation of glucagon secretion resulting from chronic hyperglycemia but did not affect the hypersecretion of insulin." (PMID 30415925, 2019). "The glucagonostatic effect of GLP-1 is dependent on the plasma glucose concentration and GLP-1 inhibits glucagon secretion during euglycemia and hyperglycemia but does not affect glucagon secretion when glucose levels are in the hypoglycemic range (≤3.7 mmol/L)." (PMID 31443356, 2019). "Increased plasma glucagon and beta hydroxybutyrate levels as well as a number of characteristic metabolomic changes characterized the 2-year-old MIDY pig with limited insulin treatment as a clinically relevant model of chronic insulin insufficiency and hyperglycemia." (PMID 28752056, 2017). "The up-regulation of several hormones (glucagon, growth hormone, catecholamines, and glucocorticoids), inflammatory mediators (interleukin (IL)-1, IL-6, Intercelluar Adhesion Molecule (ICAM-1), and tumor necrosis factor (TNF)-alpha) accompanies the development of hyperglycemia." (PMID 27110221, 2016). "Additional alterations include hyperglucagonaemia and a lack of glucagon suppression at high glucose levels, which may contribute to hyperglycaemia in these patients." (PMID 26108563, 2015). "As compared to LZ, OZ exhibited increased hyperglycemia after hemorrhage, which may be due to impaired glucose uptake due to a greater insulin suppression and/or baseline insulin resistance in OZ, but not glucagon secretion." (PMID 25472607, 2014). "In contrast, islets in diabetic mice with severe hyperglycemia were typically either heavily infiltrated with minimal to no presence of glucagon-positive cells (insulitic) or exhibited no insulitis but glucagon-positive cells redistributed throughout the core of the islets (post-inflammation)." (PMID 25101835, 2014). "In T2D, glucagon secretion in vivo is often stimulated rather than inhibited during hyperglycemia." (PMID 24315372, 2013). "Administration of glucagon to elevate HR in a beta-blocked patient can induce hyperglycemia, and so it should not be overlooked that OXM may have clinical value for these situations as OXM has antidiabetic properties associated with activating the GLP-1R." (PMID 24303183, 2013). "Later on, with the decrease of serum insulin concentration and increase of α-cells, insulin could no longer efficiently suppress glucagon secretion, thus serum glucagon levels were high even in the presence of hyperglycemia." (PMID 22586489, 2012). "Furthermore, a non-peptide compound with antagonistic activity against glucagon was developed and shown to effectively suppress glucagon-induced glucose production and subsequent hyperglycemia in normal human subjects." (PMID 23226550, 2012). "In addition, the VLCD-induced reduction in fasting hyperglycemia was observed without any changes in hepatic ceramide content, hepatic inflammatory cytokine concentrations, or plasma concentrations of glucagon, corticosterone, or fibroblast growth factor-21 (FGF-21)." (PMID 41009753, 2025).
Hyperglycemia (continued). "In this regard, D. officinale has been demonstrated to exhibit promising anti-hyperglycemia activity, such as not significantly reducing blood glucose and insulin levels in normal mice while increasing serum insulin levels and reducing serum glucagon levels in streptozotocin-induced diabetic rats." (PMID 37361228, 2023). "Notably, the fasting circulating glucagon levels in the OMPlox/lox;GCGcre/w mice were similar to those in the wild-type OMPlox/lox mice, but the degree of hyperglucagonemia induced by STZ was significantly reduced in the former, resulting in significant resistance against STZ-induced hyperglycemia." (PMID 36104518, 2022). "Given that increased glucagon secretion during DKA contributes to metabolic deterioration alongside insulin deficiency, therapeutic strategies targeting hyperglucagonemia—rather than focusing solely on hyperglycemia and insulin replacement—may offer additional clinical benefit." (PMID 41149695, 2025). "The actions of GLP-1 and GIP on glucagon secretion are different, since GLP-1 suppresses glucagon during hyperglycemia, but not at a normal fasting plasma glucose concentration." (PMID 35054422, 2021). "Lastly, we wished to confirm that PACAPVMH neurons are not affecting glucagon secretion, for which an IPGTT cannot be used since the hyperglycaemia itself would reduce this hormone." (PMID 30425681, 2018). "In fact, while GLP-1 constantly inhibits glucagon secretion, GIP has a bi-directional effect: it stimulates glucagon secretion only under conditions of normoglycemia and hypoglycemia, but not in the presence of hyperglycemia." (PMID 37729025, 2023). "However, in the present study we observed that GcgKO mice lacking both glucagon and GLP-1 developed hyperglycaemia upon hSTZ-induced beta cell ablation." (PMID 27053237, 2016).